REN (renin)
Diseases named in the same sentence as REN in open-access papers (continued):
Sharing a sentence is not in itself a finding about the gene and the disease.
schizophrenia (5 papers, 2017 to 2024). A major psychotic disorder characterized by abnormalities in the perception or expression of reality. "These pathways included the serotonergic synapse, ubiquitin mediated proteolysis, hedgehog signaling, renin secretion and adipocytokine signaling, all of which have been implicated in schizophrenia and/or related phenotypes." (PMID 28221366, 2017). "Most antipsychotic agents utilized in the treatment of schizophrenia, bipolar disorder, and other psychoses are dopaminergic antagonists that interact with the renin–angiotensin–aldosterone system, hence disrupting the regulation of BP." (PMID 39727798, 2024). "Possible biological mechanisms can involve the central renin-angiotensin system, which affects inflammation and immunity that contribute to the development of schizophrenia." (PMID 39567981, 2024). "Schizophrenia kinases aligned with ErbB (p = 3.47E-43), gonadotropin-releasing hormone (p = 1.94E-38), and renin-angiotensin (p = 3.62E-38) signaling." (PMID 28900113, 2017).
Shock (5 papers, 2018 to 2024). The state in which profound and widespread reduction of effective tissue perfusion leads first to reversible, and then if prolonged, to irreversible cellular injury. "In response to low blood pressure and/or a decrease in extracellular fluid volume (as it occurs during dehydration, hypotension, or septic shock) JG cells respond by releasing renin to the circulation to reestablish homeostasis." (PMID 33790364, 2021). "A further effector mechanism in the hemorrhagic shock, which was analyzed, is the renin-angiotensin system." (PMID 30071054, 2018). "Lack of macula densa NOS1 inhibited renin release and delayed the recovery of blood pressure following hemorrhagic shock." (PMID 37553306, 2023).
systolic heart failure (5 papers, 2015 to 2023). Heart failure caused by abnormal myocardial contraction during systole leading to defective cardiac emptying. "The mechanical dyssynchrony caused by chronic RVP is distinctly different to the neurohormonal mechanisms underpinning the improvement associated with renin-angiotensin-aldosterone system inhibition in other forms of systolic heart failure." (PMID 37124556, 2023). "In systolic heart failure, due to a significant reduction of cardiac output, a vicious cycle with neurohormonal induction and the renin-angiotensin-aldosterone system as the central link is formed, with strong association with poor outcome in HF." (PMID 36824173, 2023). "However, the implications of SZC in up-titrating renin–angiotensin–aldosterone system inhibitors in patients with systolic heart failure remain unknown." (PMID 34884224, 2021).
tuberculosis (5 papers, 2020 to 2024). A chronic, recurrent infection caused by the bacterium Mycobacterium tuberculosis. "The pathways regulated by MCODE 4 include renin secretion, tuberculosis, regulation of lipolysis in adipocytes, and neuroactive ligand-receptor interaction." (PMID 35936218, 2022).
advanced heart failure (4 papers, 2016 to 2025). Patients with advanced heart failure have severe limitations, experiences symptoms even while at rest and are mostly bedbound patients. "Reduced ejection fraction in advanced heart failure leads to organ hypoperfusion and activation of the renin–angiotensin–aldosterone system, further accelerating disease progression." (PMID 41515189, 2025).
arterial disease (4 papers, 2017 to 2025). "These include reductions in BP (by suppressing renin secretion) and reductions in inflammation, a significant factor in the progression of atheromatous arterial disease." (PMID 40647207, 2025). "Our results highlighted the critical roles of renin in AAA disease, which raised cautionary concerns about the applications of direct vasodilators on AAA and other arterial diseases." (PMID 37383707, 2023). "In addition, patients with PAD also showed increased PRL and PRA compared to VV disease, which raised cautionary concerns about increased renin phenotypes and applications of direct vasodilators in PAD and other arterial diseases." (PMID 37383707, 2023). "Considering the critical role of renin in vascular disease, the PAD and VV groups were roughly combined into the non-AAA group to exclude the bias of the plasma renin level and activity in arterial disease." (PMID 37383707, 2023).
Arthritis (4 papers, 2021 to 2026). Inflammation of a joint. "Serum renin and ACE levels were similar in arthritis patients and in healthy controls in contrast with higher levels in synovial fluid of arthritis patients." (PMID 37878123, 2023). "Conversely, the blockade of the renin-angiotensin system (RAS) has been suggested to dampen inflammation and protect against arthritis." (PMID 34063142, 2021).
autoimmune disease (4 papers, 2014 to 2025). A disorder resulting from loss of function or tissue destruction of an organ or multiple organs, arising from humoral or cellular immune responses of the individual to their own tissue constituents. "Because renin is reported to be involved in autoimmune diseases, we collected oral biopsies from patients with OLP and healthy individuals, sampled from clinically lesion and unaffected mucosa, to test renin expression in these tissues." (PMID 32213463, 2020). "Because the pathogenesis of the autoimmune diseases caused by immunization with renin or AN1792 could not be fully elucidated, the development of renin vaccines was stalled for a long time." (PMID 31485348, 2019). "In addition to playing a known role in circulatory regulation, RAS has been emphasized to result in autoimmune disorders recently by some studies that suggest RAS facilitates colitis through activating Th17 cells, and renin expression is significantly increased in inflamed colonic tissues." (PMID 32213463, 2020).
cocaine addiction (4 papers, 2021 to 2024). "KEGG pathway enrichment analysis revealed significant roles in fat cells, including gastric acid secretion, cocaine addiction, renin secretion, and lipolysis regulation." (PMID 38674408, 2024). "Furthermore, in KEGG pathway enrichment, gastric acid secretion, cocaine addiction, renin secretion, and regulation of lipolysis in adipocytes were enriched with the highest p-values." (PMID 38674408, 2024).
colon cancer (4 papers, 2017 to 2023). "Combination of Losartan and 5-FU revealed synergistic and additive anti-tumorigenic properties, suggesting that targeting of the renin-angiotensin system presents a potentially new therapeutic strategy in colon cancer treatment." (PMID 33883980, 2021). "Interestingly, it was reported that the angiotensin activation ability in CT26 mouse colon cancer cells was dependent mainly on the renin-chymase pathway, rather than the renin-ACE pathway." (PMID 37175975, 2023).
endometriosis (4 papers, 2012 to 2025). The growth of functional endometrial tissue in anatomic sites outside the uterine body. "In particular, in PCOS, which is frequently associated with endometriosis, the use of SP has been proposed not only as an anti-androgen, but also as an anti-MR, to reduce the side effects related to the activation of the renin-angiotensin-aldosterone system, represented by increased ARR." (PMID 36613755, 2022). "KEGG analysis demonstrated that DEGs between the endometriosis subtypes were enriched in gap junction, viral protein integration with cytokine and cytokine receptor and renin-angiotensin system." (PMID 39744159, 2025). "On the contrary, renin levels were significantly lower in patients with endometriosis than in controls (15.9 ± 7.6 vs. 23.4 ± 8.3 mIU/L, p = 0.0055)." (PMID 36613755, 2022). "Aldosterone values were similar in the two groups, while renin was significantly lower and the aldosterone to renin ratio was significantly higher in patients with endometriosis than in controls." (PMID 36613755, 2022). "Deregulation of the renin-angiotensin-system plays a role in the pathophysiology of endometriosis and pre-eclampsia." (PMID 22662209, 2012). "Our results show that plasma aldosterone concentrations were increased at the limit of significance (p = 0.0548) in patients with endometriosis, while renin levels were significantly reduced and the ARR was significantly increased compared with healthy controls." (PMID 36613755, 2022). "Physiological Studies: Women diagnosed with endometriosis demonstrate aberrant RAS activity, characterized by reduced plasma renin levels, elevated aldosterone-renin ratios, and increased systolic blood pressure." (PMID 40725782, 2025).
glucocorticoid deficiency (4 papers, 2009 to 2023). "Familial glucocorticoid deficiency (FGD) is a rare autosomal recessive disorder characterized by isolated glucocorticoid deficiency in the presence of normal plasma renin and aldosterone level." (PMID 23232022, 2012). "Familial glucocorticoid deficiency (FGD) is a rare autosomal recessive disorder characterized by isolated glucocorticoid deficiency in the presence of normal plasma renin and aldosterone level resulting from ACTH resistance." (PMID 23232022, 2012).
hyperhomocysteinemia (4 papers, 2021 to 2025). A serious metabolic condition caused by mutations in the MTHFR gene, medications, or nutritional deficiency. "Some studies demonstrate the impact of hyperhomocysteinemia on the autonomic nervous system via activation of the renin-angiotensin-aldosterone system and the development of sympathicotonia." (PMID 40134906, 2025).
infantile hemangioma (4 papers, 2015 to 2021). "Components of the renin–angiotensin system (RAS) have been shown to be expressed by similar populations in infantile hemangioma, pyogenic granuloma, and venous malformation." (PMID 33816543, 2021). "The role of the renin–angiotensin system (RAS) in the biology of infantile hemangioma (IH) represents an emerging paradigm, particularly the involvement of renin, angiotensin converting enzyme, and angiotensin II." (PMID 26137466, 2015). "Propranolol treatment suppressed plasma renin activity, reduced aldosterone secretion, and downregulated renin–angiotensin–aldosterone (RAA) axis components, angiotensin-converting enzyme and angiotensin II receptor-2 to control infantile hemangioma." (PMID 33419318, 2020).
keloid (4 papers, 2019 to 2025). An irregularly shaped, elevated mark on the skin caused by deposits of excessive amounts of collagen during wound healing. "Studies on the effect of renin-angiotensin system modulating agents on keloid lesions and hypertrophic scars." (PMID 32039229, 2019). "Transforming growth factor-β (TGF-β), connective tissue growth factor (CTGF), vascular endothelial growth factor (VEGF) and the renin–angiotensin system were reported to be potential targets in keloid management considering their participation in wound healing and keloid formation." (PMID 35012558, 2022). "GO and KEGG enrichment analyses of the DEGs revealed that signaling pathways such as FA, mineral absorption, renin secretion, and the TGF‐β signaling pathway are closely related to the formation of keloids." (PMID 41278551, 2025).
leishmaniasis (4 papers, 2021 to 2025). Infectious disease that is transmitted through the bite of hematophagous female phlebotomine sand flies. "DEGs were enriched in pathways related to chemokine signaling, melanogenesis, leishmaniasis, graft-versus-host disease, allograft rejection, tyrosine metabolism, the renin–angiotensin system, and retinol metabolism." (PMID 40004551, 2025).
membranous nephropathy (4 papers, 2014 to 2024). "The KDIGO guideline recommends implementing general measures for membranous nephropathy patients, emphasizing the renin-angiotensin axis inhibitors, blood pressure control, and dietary recommendations regarding sodium and protein intake." (PMID 39079141, 2024).
obstructive uropathy (4 papers, 2018 to 2020). "Renal parapelvic cysts are located close to the collecting system and this often causes discomforting features, such as flank pain, hematuria, infection, urinary obstruction, and renin-mediated hypertension." (PMID 33128007, 2020). "Our main findings suggested that during the pro-inflammatory phase of obstructive uropathy, where the tubular remodeling is also observed, the iRAS is activated in the cortex as reflected by the increase in renin in dilated proximal tubules." (PMID 31803050, 2019).
ovarian carcinoma (4 papers, 2016 to 2022). A malignant neoplasm originating from the surface ovarian epithelium. "Our results support the idea that a panel of tumor-related proteins, including heterogeneously expressed proteins such as renin, ACVR1, TLR1, and KLKs,5,7,11 may encompass tumor heterogeneity in ovarian cancer patients." (PMID 34868557, 2021). "A local renin–angiotensin system (RAS) has been found in the ovary, and changes in selected components of this system were observed in pathological states and also in ovarian cancer." (PMID 35008474, 2021). "But there might be coherence as sPRR is an important factor in the renin-angiotensin system (RAS), Wnt-cascade, and activation of mitogen-activated protein kinase (MAPK) which all have been shown to be upregulated in ovarian cancer." (PMID 27660742, 2016).
Polyuria (4 papers, 2014 to 2023). An increased rate of urine production. "The initial molecular event that leads to the development of polyuria is the upregulation of renin in the kidney and the brain, which is caused by VDR inactivation." (PMID 24911026, 2014). "Oxidative stress, sleep disturbances, and increased sympathetic activity together with the renin–angiotensin–aldosterone system might be important in NE pathophysiology and nocturnal polyuria; however, it is unknown what is cause and what is the consequence." (PMID 37140712, 2023). "Acute increases in plasma and extracellular and intracellular Ca2+ concentrations also inhibit renin secretion in renal proximal tubular cells, but long-term Ca2+ elevation can cause elevated PRA, which may be a compensation mechanism caused by Ca2+-mediated polyuria." (PMID 32973674, 2020).
post-traumatic stress disorder (4 papers, 2016 to 2024). An anxiety disorder precipitated by an experience of intense fear or horror while exposed to a traumatic (especially life-threatening) event. "The renin-angiotensin system is implicated in extinction learning in posttraumatic stress disorder." (PMID 26969407, 2016).
primary hyperparathyroidism (4 papers, 2010 to 2025). "In primary hyperparathyroidism, an increased risk of developing the cardiovascular disease may exist due to increased activity of the renin-angiotensin-aldosterone system." (PMID 36389124, 2022). "Our results showed a strong positive correlation between PTH and renin concentration in patients with primary hyperparathyroidism." (PMID 36389124, 2022). "How aldosterone excess may relate to hypercalcaemic hyperparathyroidism is less clear, but previous studies have demonstrated markedly decreased plasma aldosterone and renin levels as well as decreased blood pressure in patients with primary hyperparathyroidism after parathyroidectomy." (PMID 40608198, 2025).
pulmonary embolism (4 papers, 2015 to 2024). The obstruction of the pulmonary artery or one of its branches by an embolus, sometimes associated with infarction of the lung. "The proposed mechanisms were cocaine induced pulmonary embolism and cardiac toxicity from sympathetic system and renin-angiotensin system activation." (PMID 25918664, 2015).
renal carcinoma (4 papers, 2004 to 2026). A carcinoma arising from the epithelium of the renal parenchyma or the renal pelvis. "The majority of the ACA variants were found to co-occurred in ACC (n = 36/42) and were benign, except for two of unknown significance in KANK1 and REN genes, described as associated with renal cancer." (PMID 41806143, 2026). "The renin-angiotensin system regulates angiogenesis, cell differentiation and proliferation, opening a new avenue for understanding the occurrence of renal carcinoma." (PMID 34358255, 2021). "Lu-12, REN-9, Ren-10 map within cancer tumor suppressor gene locus at chromosome 3p21.3, a region often deleted in small cell lung cancer as well as in renal cancer." (PMID 15541172, 2004).
retinopathy of prematurity (4 papers, 2015 to 2025). A bilateral retinopathy characterized by neovascularization, scarring, retinal detachment, and eventually blindness. "Retinopathy of prematurity (ROP) is a major cause of childhood blindness worldwide, linked to gene variants in the renin–angiotensin–aldosterone system, including angiotensin-converting enzyme (ACE) and angiotensin II receptor type 1 (AGTR1)." (PMID 39186201, 2025). "It has also been experimentally shown that the blockade of the renin-angiotensin system, not only targets pathological angiogenesis but also promotes re-vascularization of the retina and are likely to prove important in the treatment of those suffering from retinopathy of prematurity." (PMID 30460043, 2018). "Previous studies done in our lab has shown the presence multifold raised levels of renin angiotensin components in the vitreous of retinopathy of prematurity (ROP) patients and retinoprotective effect of the ACE inhibition in the animal model of ROP." (PMID 30460043, 2018).
SARS-CoV infection (4 papers, 2020 to 2022). "ACE2 has an important role regulating the renin-angiotensin system (RAS), and it is confirmed that SARS-CoV infection reduces ACE2 expression and attenuates acute lung failure through blocking the renin–angiotensin pathway." (PMID 33080900, 2020). "Human angiotensin-converting enzyme 2 (ACE2), a type I transmembrane receptor physiologically acting as a carboxypeptidase enzyme within the renin-angiotensin system (RAS), is a critical mediator of infection by several severe acute respiratory syndrome (SARS) corona viruses." (PMID 36056420, 2022). "They believed that the negative effect of SARS-CoV infection on the renin-angiotensin system might be mediated by modulating ACE2 activity, which may cause severe acute lung failure." (PMID 34025650, 2021).
sickle cell disease (4 papers, 2017 to 2026). Sickle cell anemias are chronic hemolytic diseases that may induce three types of acute accidents: severe anemia, severe bacterial infections, and ischemic vasoocclusive accidents (VOA) caused by sickle-shaped red blood cells obstructing small blood vessels and capillaries. "This null association did not change after excluding low-dose renin-angiotensin system inhibitors or including an interaction term with sickle cell disease therapies." (PMID 41563849, 2026). "We previously showed pregnant women with sickle cell disease to have a relatively low plasma renin concentration in late pregnancy, associated with a lack of the expected plasma volume expansion." (PMID 28880908, 2017).
Thromboembolism (4 papers, 2020 to 2022). The formation of a blood clot inside a blood vessel that subsequently travels through the blood stream from the site where it formed to another location in the body, generally leading to vascular occlusion at the distant site. "Dysfunction of ACE2 leads to abnormal renin-angiotensin (RAS) system activation, which promotes platelet adhesion and aggregation and enhances the risk of thromboembolism following the invasion of SARS-CoV-2." (PMID 34031269, 2021).
thrombotic microangiopathy (4 papers, 2018 to 2026). The syndromes of microangiopathic hemolytic anemia, thrombocytopenia, and variable signs of organ impairment, due to platelet aggregation in the microcirculation. "In summary, we reported here that renin-positive RLCs from the afferent arterioles repopulate damaged glomeruli in a thrombotic microangiopathy-like kidney-specific EC injury model." (PMID 29771991, 2018). "Additionally, this therapy has recently demonstrated renal benefits in thrombotic microangiopathy with HE compared with conventional renin–angiotensin system inhibitors." (PMID 41680667, 2026).